TRGJP1 (T cell receptor gamma joining P1)
Synonyms: JP1; TCRGJP1
Gene: T-cell receptor joining (J) gene on chromosome 7 (38,276,259 to 38,276,318, reverse strand). Ensembl gene ENSG00000211692.
Diseases named in the same sentence as TRGJP1 in open-access papers:
TRGJP1 is named in the same sentence as 1 disease in open-access papers, as found by Europe PMC text mining. Sharing a sentence is not in itself a finding about the gene and the disease.
TRGJP1 shares sentences with these, for which no sentence is quoted: psoriasis (1 paper).